NEAT1 (nuclear paraspeckle assembly transcript 1)
Diseases named in the same sentence as NEAT1 in open-access papers (continued):
Sharing a sentence is not in itself a finding about the gene and the disease.
cancer (continued). "These lncRNAs can be either upregulated (e.g., ANRIL, SNHG12, NEAT1 in some cancers, PVT1) or downregulated (e.g., GAS5, NEAT1 in APL) in order to promote cell proliferation and migration, and prevent apoptosis of cancerous cells." (PMID 30654440, 2019). "Nuclear paraspeckle assembly transcript 1 (abbreviated as NEAT1), located on chromosome 11 (11q13.1), is one of nuclear lncRNAs and has been identified to play crucial roles in various cancers." (PMID 30575330, 2019). "LncRNAs such as NEAT1, UCA1, and PVT-1 have been shown to regulate drug resistance in multiple cancer types through different molecular mechanisms." (PMID 35582574, 2019). "To investigate the clinical significance of NEAT1, we analyzed its expression levels in a publicly available dataset and in 71 CRC samples from Fudan University Shanghai Cancer Center." (PMID 30185232, 2018). "Therefore, NEAT1 may be possibly used as a biomarker for the existence of primary cancer." (PMID 30374364, 2018). "Further research is needed to determine if NEAT1 plays a direct role in oncogenesis, or if instead the MALAT1/NEAT1 locus is under mutual regulation, with NEAT1 upregulation in cancer being a byproduct of its genomic proximity to MALAT1." (PMID 29113413, 2017). "In the process of lncRNA-dependent nuclear body assembly, NEAT1 directly interacts with the SWI/SNF core unit, BRG1 or BRM, to form the paraspeckle structure, which leads to cell cycle arrest and affects cancer progression." (PMID 28212646, 2017). "Therefore, NEAT1 might also be a tumor marker for predicting tumorigenesis and cancer progression." (PMID 28507281, 2017). "Upregulated NEAT1 in NPC cells inhibited the targeting of miR-204 to ZEB1, an important modulator of EMT in cancer cells, resulting in radioresistance and EMT activation." (PMID 28872613, 2017). "Recently, the lncRNAs, nuclear paraspeckle assembly transcript 1 (NEAT1), was reported to have a role in cancer prognosis and chemo-/radio-sensitivity in a substantial number of studies." (PMID 27926523, 2017). "The results suggested that NEAT1 was remarkably down-regulated in ESCA and HCC, while in PC, the expression level of NEAT1 was higher in cancer samples than that in normal specimens." (PMID 28118609, 2017). "Twelve studies including 3,262 patients were pooled in this study, and the results indicated that elevated NEAT1 expression was significantly correlated with poor prognosis, progression, LNM and DM in patients with various types of cancer." (PMID 29026116, 2017). "In the current study, we determined the expression levels of NEAT1 in clinical NPC tissue samples and normal nasopharyngeal epithelial tissues and found that its expression was reduced in carcinoma tissues." (PMID 29050268, 2017). "Several cancer-related long non-coding RNAs have been reported to be correlated with GAC proliferation or metastasis, including HOTAIR, ANRIL, MRUL, CCAT1, NEAT1 and HULC, etc.." (PMID 26911892, 2016). "The total fraction lncRNA-derived reads varied between cancers (P<1e-99, one-way ANOVA), to a large extent explained by abundant MALAT1 or NEAT1 in some types." (PMID 28959951, 2016). "A total of 9 CARs overlapped with annotated lncRNAs, of which NEAT1, MALAT1, and MEG3 are known to be regulated by cancer pathways." (PMID 25264628, 2014). "Moreover, NEAT1‐31 and anti‐CD47 promoted the elimination of cancer cells and prolonged the survival time of mice with BRCA and GBM." (PMID 40344649, 2025). "Interestingly, wo found that XIST, SNHG14, NEAT1, LINC00943, KCNQ1OT1 have pro-tumor functions in various cancers but DHRS4-AS1 can inhibit tumor development." (PMID 40015977, 2025). "This comprehensive analysis identified a batch of core lncRNAs that exhibited strong associations and high regulatory potential across multiple cancers, including NEAT1, MALAT1, GAS5, TP53TG1, and LINC00941, many of which have been previously confirmed to be closely related to cancer progression." (PMID 41373831, 2025).
cancer (continued). "NEAT1, among other lncRNAs, holds promise as a therapeutic target in both cancers and non-cancerous diseases." (PMID 40362651, 2025). "The high clonogenic activity of HAN-1 cells can be related to increased expression of several long non-coding RNAs, such as TUG1, MEG3, MALAT1, NEAT1, and DANCR – all considered as modulators of stemness of cancer cells, their differentiation potential and chemoresistance." (PMID 38342891, 2024). "For instance, knocking out NEAT1 and MALAT1 from the promoter region inhibits cancer metastasis." (PMID 39257589, 2024). "High levels of NEAT1 induce chemotherapeutic resistance by regulating several cellular processes, including DNA damage repair, cell cycle, apoptosis, autophagy, DNA damage repair, EMT, cancer stem cell characteristics, and drug metabolism and transportation." (PMID 39246994, 2024). "Neat1, the most significantly upregulated DEG in OLGs after 2VO surgery, is a long noncoding RNA that is essential for the formation of paraspeckles and interacts with many intracellular regulatory factors that has been widely investigated in the cancer field." (PMID 38180614, 2024). "Supported by TCGA data, NEAT1 and MALAT1 expressions could predict A3B activity, aiding in evaluating cancer progression and response to A3B-targeted therapies." (PMID 39322638, 2024). "The positive rate of NEAT1-expressing tissues in cancer samples was ~ 3 folds of that in the adjacent non-tumor tissues." (PMID 37986114, 2023). "Moreover, by participating in the phosphorylation of MAPK and Akt, NEAT1 also regulates NSCLC progression, introducing a new avenue for cancer pathogenesis." (PMID 38152110, 2023). "Moreover, NEAT1 in combination with specific pathways, such as miR-129/ZEB2 and miR-211/HMGA2 are participated in the chemotherapy drug resistance in cancer cells." (PMID 37310654, 2023). "In addition, some lncRNAs, such as HOTAIR, NEAT1, MALAT1 and MEG3, have been shown to play positive or negative regulatory roles during malignant tumor progression." (PMID 38152110, 2023). "Moreover, we observed a negative correlation between the XBP1s/u ratio and the Delta Ct values of lncRNAs NORAD, NEAT1, and LINC00299, representing their gene expression levels in cancer tissues." (PMID 37706018, 2023). "NEAT1 (nuclear paraspeckle assembly transcript 1) is significantly increased in non-alcoholic fatty liver disease (NAFLD) and its’ high expression is correlated with worse survival in cancer patients." (PMID 37093889, 2023). "Finally, similarly to NEAT1 and MALAT1, aberrant Xist expression has been reported in numerous cancer types where it is mainly found overexpressed and acting as an oncogene by interfering with miRNA regulation." (PMID 37444543, 2023). "Like NEAT1, MALAT1 is upregulated in superclusters A and B compared to C. Its effects are manifold and some controversy exists about its activities in different cancer types and settings." (PMID 38066300, 2023). "Thus, the combination treatment strategy for cancers, especial HCC, by inhibiting NEAT1 and KIF11, has great potential for clinical application." (PMID 37752791, 2023). "Recently, there is a research discovering that miR-582-5p can be targeted by lncRNA nuclear paraspeckle assembly transcript 1 (NEAT1) to promote the epithelial-mesenchymal transition (EMT) of lung bronchial epithelial cells and the acquisition of cancer stem cell-like characteristics." (PMID 36540097, 2022).
cancer (continued). "Consistently, analysis of the Cancer Cell Line Encyclopedia (CCLE) metabolomic dataset 50 of HCC cell lines showed that glycolysis and Warburg effect pathways were up-regulated in HCC cells exhibiting low NEAT1 expression." (PMID 35547764, 2022). "We have no clue about the binding RNAs in other cancer, but the role of NEAT1 in BC needs to be re-examined." (PMID 35687898, 2022). "Furthermore, NEAT1, MALAT1, XIST, and PKD had reported or validated having a close relation with pro chemotherapy resistance of malignant tumors." (PMID 35873473, 2022). "Through utilizing starBase (selection condition: CLIP-Data > = 5; pan-Cancer > = 4), three lncRNAs (FGA5-AS1, NEAT1 and SNHG16) that could bind to miR-124-3p were predicted." (PMID 35761386, 2022). "Further investigation revealed that NEAT1 enhanced RCC cell proliferation, migration, invasion, and EMT, and inhibited cell cycle progression by sponging miR-34a, thus increasing the expression level of c-Met, a potential therapeutic target in cancers." (PMID 34512157, 2021). "However, genes associated with cell differentiation (EPCAM, CK8, CK18, and FOXA2), EMT (SNAI1, FOSL1, and ID1), and cancer stem cells (CD44, CD133, ETV1, MALAT1, NEAT1, and NESTIN) displayed a more varied response compared to 2D cells." (PMID 33356003, 2021). "In fact, expression of NEAT1 (which isoform was not specified) increased tumour growth and chemoresistance in a variety of cancers, such as breast cancer and non-small cell lung cancer (NSCLC)." (PMID 33143162, 2020). "Further understanding of the regulation of NEAT1 and UPR by resveratrol may provide a therapeutic strategy for cancer treatment." (PMID 33267910, 2020). "Therefore, the oncogenic lncRNA NEAT1 seems to be independently stabilized by two different RBPs, by HuR and SRSF1, which are both frequently overexpressed in cancer." (PMID 32340118, 2020). "In several genomic loci, NEAT1 colocalize with MALAT1 with independent but correlative activities, and it is involved in the regulation of different genes, including some genes controlling cancer progression." (PMID 33193626, 2020). "In 24 types of human cancer, first, we compared NEAT1 expression between normal and tumor tissues using TCGA datasets (nine cancer tissues were excluded due to no normal sample)." (PMID 31186635, 2019). "Through gene expression analysis in 24 cancer types using TCGA datasets, we revealed that NEAT1 expression was decreased in five cancer tissues (BRCA, CHOL, PCPG, ESCA, and THYM) and increased in five cancer tissues (KICH, KIRC, KIRP, LIHC, and PRAD) compared with corresponding normal tissues." (PMID 31186635, 2019). "NEAT‐1‐induced sponging of miR‐448 removes the inhibitory effect of this miRNA on ZEB1, thus upregulating this transcription factor responsible for cancer progression by promoting EMT." (PMID 30430751, 2019). "In most cancer types, NEAT1 seems to be upregulated in cancer tissue compared to the corresponding noncancerous tissue as well as in the investigated cancer cell lines." (PMID 30430751, 2019). "Not surprisingly, NEAT1 silencing by siRNA sensitized tumor cells to anti-cancer drugs such as sorafenib, cisplatin, dexamethasone, and paclitaxel." (PMID 30374364, 2018).
cancer (continued). "Moreover, due to the wide activation of NF-κB in cancers, the efficiency of Galectin-3/TLR4/NF-κB/NEAT1 path should be compared with NF-κB activation induced by other factors in vitro and in vivo." (PMID 29788922, 2018). "Of special note, the close proximity of NEAT1 to MALAT1, and their similar roles as oncogenes in multiple cancers suggests that the entire locus may be subject to aberrant regulation in cancer." (PMID 29113413, 2017). "A likely lncRNAs profile will include, among others, HOTAIR, MEG3, NEAT1, UCA1, and/or AK126698 in cancer-drugs cisplatinum-based therapies, and the recently proposed GAS5, UCA1, BC087858 and SOX2-OT involved in the gene-target therapies as EGFR-TKIs based oncological treatments." (PMID 28904641, 2017). "The results from stratified analyses suggested that different detection methods and sample size (more or less than 100) do not alter the predictive value of NEAT1 on the OS for all involved cancers." (PMID 29026116, 2017). "Subgroup analysis showed that NEAT1 detection method (qRT-PCR) and sample size (more or less than 100) did not alter the predictive value of NEAT1 on OS in various cancers." (PMID 29026116, 2017). "NEAT1 is involved in ceRNA network in several cancers; however, data in MM are virtually absent." (PMID 41928426, 2026). "We hypothesized that NEAT1‐31‐mediated activation of PI3K–AKT enhances phagocytosis in macrophages that recognize cancer cells, however not in macrophages that are not activated by tumor ligands." (PMID 40344649, 2025). "Therefore, the regulation of NEAT1 and paraspeckles formation indicates a novel mechanism by which MUC1-CT may influence cancer biology, suggesting the potentiality of targeting these signaling pathway for future treatments in PDAC." (PMID 40001578, 2025). "Moreover, analysis of patients with grade 3 TNBCs treated with cytotoxic anti-cancer agents demonstrated that those with MUC1-high and NEAT1-high tumors had significantly decreased relapse-free survival, supporting involvement of the MUC1-C/NEAT1 pathway in conferring chemoresistance." (PMID 38802648, 2024). "Moreover, nuclear-enriched abundant transcript 1 (NEAT1) was found to sponge miR-1321 and thus regulate the expression of the tight junction protein 3 (TJP3) (an important factor in cancer development), resulting in EMT promotion, invasion, and migration of OC cells." (PMID 37373222, 2023). "Moreover, several studies have confirmed that lncRNA Neat1 could sponge miR-185-5p to regulate IGF2 expression or DNMT1/mTOR signaling, promoting cancer progression." (PMID 35501920, 2022). "However, in light of the NEAT1_1 role in cancer cell metabolism, the contribution from specific NEAT1 isoforms is no longer clear." (PMID 36139550, 2022). "Therefore, in cancer cells exposed to arecoline, JunD is activated not by phosphorylation alone but by interaction with NEAT1 to suppress the expression of ZO-1 and destabilize structural integrity of TJs." (PMID 34316331, 2021). "Moreover, several lncRNAs that have been previously reported to be involved in various cancers as PVT1, HOTAIR, NEAT1, and MALAT1 may contribute to cancer development and progression." (PMID 33670447, 2021). "Interestingly, total NEAT1 expression showed a different distribution among the PAM50 subtypes compared to NEAT1_2, being most highly expressed in luminal A, luminal B, and normal-like cancers." (PMID 31992741, 2020).